GSDMD (gasdermin D)
Diseases named in the same sentence as GSDMD in open-access papers (continued):
Sharing a sentence is not in itself a finding about the gene and the disease.
atherosclerosis (43 papers, 2020 to 2026). A disease characterized by the build-up of fatty material and calcium deposition in the arterial wall resulting in partial or complete occlusion of the arterial lumen. "To examine the effect of GSDMD on GI‐Y2‐mediated vasoprotection, we examined the function of GI‐Y2 in atherosclerosis with Gsdmd deficiency (Gsdmd−/−ApoE−/−)." (PMID 40045452, 2025). "We aimed to develop new inhibitor of GSDMD in atherosclerosis, as well as clarify the mechanisms underlying this inhibiting effect." (PMID 40045452, 2025). "Recently, we reported that the expression of GSDMD is increased in atherosclerosis and that GSDMD deficiency ameliorates atherosclerotic plaque formation." (PMID 40045452, 2025). "Recent studies in apoE–/– KO mice using chemical or adenovirus associated inhibition of GsdmD expression also showed a reduction in atherosclerosis." (PMID 34395445, 2021). "Mechanistically, we found that gasdermin D was downstream of caspase-11 activation and induced pyroptosis in lipid-loaded macrophages and that caspase-11 deficiency blocked the activation of gasdermin D in atherosclerosis." (PMID 33981234, 2021). "The study also found that the GSDMD-specific inhibitor GI-Y1 can effectively reduce the progression of atherosclerosis." (PMID 40356915, 2025). "This work demonstrated that GI‐Y2 can potentially alleviate atherosclerosis by targeting GSDMD and provided a new inhibitor for the study of GSDMD‐mediated pyroptosis." (PMID 40045452, 2025). "Using single‐cell RNA sequencing, we previously confirmed that the expression of GSDMD is principally increased in macrophages in atherosclerosis." (PMID 40045452, 2025). "ox-LDL has been implicated in aberrant activation of NLRP3, which, in turn, activates GSDMD and exacerbates atherosclerosis in both mouse models and humans." (PMID 40244103, 2025). "Our previous study showed that GSDMD mediated the infiltration and migration of macrophages during atherosclerosis." (PMID 40045452, 2025). "Given that GSDMD is principally distributed in macrophages during atherosclerosis, we constructed macrophage membrane‐coated GI‐Y2 nanoparticles (GI‐Y2@MM‐NPs) to enhance the targeting of GI‐Y2 to macrophages in atheromatous plaques." (PMID 40045452, 2025). "Ox-LDL, a critical lipid component in atherosclerosis, induces ROS production, which oxidizes GSDMD and activates the NLRP3 inflammasome." (PMID 40244103, 2025). "Through the activation of GPR109A, butyrate produced by L. murinus and L. johnsonii suppressed the expression of Gasdermin D (GSDMD) in the pyroptosis of macrophages during atherosclerosis." (PMID 40726432, 2025). "Through negatively regulating the Lin28/Let7 signaling pathway, overexpression of Sirt6 decreased GSDMD cleavage and pyroptosis in endothelial cells, which retarded the progression of atherosclerosis." (PMID 38172884, 2024). "Recent research has shown enhanced expression of GSDMD in atherosclerosis, where it can mediate the cGAS/STING/TBK1/IRF3/NF-κB signaling pathway, contributing to the process of atherosclerosis." (PMID 39301029, 2024). "Recent studies have shown that GSDMD-mediated pyroptosis is involved in the initiation, progression, and complications of atherosclerosis that involve the endothelial cells, macrophages, and smooth muscle cells." (PMID 36807553, 2023). "Recent studies reported that GSDMD mediates inflammation-induced defects in reverse cholesterol transport and promotes atherosclerosis." (PMID 36807553, 2023). "GSDMD as an executor of pyroptosis has recently been found to be involved in the pathogenesis of atherosclerosis." (PMID 37125240, 2023). "The expression of gasdermin D was upregulated in peripheral blood mononuclear cells (PBMCs) from patients with atherosclerosis." (PMID 37125240, 2023). "Recent studies have revealed the widespread occurrence of pyroptosis in atherosclerosis, with GSDMD showing a propensity to promote the development of atherosclerosis." (PMID 37761020, 2023).
atherosclerosis (continued). "The availability of safe, EMA- and FDA-approved drugs that inhibit GSDMD makes it an interesting therapeutic target to address pyroptosis in atherosclerosis." (PMID 35625908, 2022). "Gasdermin D (GSDMD) is involved in the development of atherosclerosis as a key protein of proptosis." (PMID 36544106, 2022). "At present, a large number of studies have shown that GSDMD, as the core protein of pyroptosis, plays an important role in the process of atherosclerosis." (PMID 36544106, 2022). "Consistent with the knockout of AIM2, knockout of Caspase-1/11 or GSDMD alleviated atherosclerosis in mice Aim2 knockout in Jak2V617Fmice." (PMID 34122076, 2021). "Recently, absent in melanoma 2 (AIM2) inflammasome, caspase 1 and 11, and GsdmD were shown to play in role in clonal hematopoiesis mediated exacerbation of atherosclerosis." (PMID 34395445, 2021). "To investigate the mechanism of GsdmD in promoting atherosclerosis, we also probed the aortic protein extracts for VCAM-1 expression levels." (PMID 34395445, 2021). "Furthermore, using Gsdmd−/−ApoE−/− mice, we ascertained that the protective effect of GI‐Y2 against atherosclerosis is mainly achieved by targeting GSDMD." (PMID 40045452, 2025). "GSDMD is principally distributed in macrophages during atherosclerosis." (PMID 40045452, 2025). "Identifying and developing new inhibitors of GSDMD could be a promising strategy for treating pyroptosis‐mediated diseases, such as atherosclerosis." (PMID 40045452, 2025). "In conclusion, characterizing GSDME- and Gasdermin D-mediated scorching in atherosclerosis progression may be a potential therapeutic approach for atherosclerosis." (PMID 39935606, 2025). "Consequently, this led to a significant reduction of GSDMD cleavage and pyroptosis in endothelial cells, catalyzing a deceleration in the progression of atherosclerosis." (PMID 38172884, 2024). "Moreover, there is evidence to suggest that GsdmD mediates inflammation-induced defects in reverse cholesterol transport and promotes atherosclerosis." (PMID 39424784, 2024). "Inhibition of GSDMD activation may therefore be a promising and potential therapeutic target for treating atherosclerosis." (PMID 37593179, 2023). "Notably, disulfiram, an FDA-approved drug, has been identified as a potent small molecule inhibitor of GSDMD pore formation, although its effects on atherosclerosis have yet to be tested." (PMID 37894840, 2023). "Furthermore, genetic inactivation of GSDMD, the pyroptosis executioner, effectively blocks the development of atherosclerosis in hyperlipidemic mice." (PMID 37894840, 2023). "Our data provide the first evidence for the role of GsdmD in promoting atherosclerosis." (PMID 34395445, 2021). "The whole-body knockout of GsdmD may alter the response of VSMCs to lipids and other inflammatory stimuli to modulate progression of atherosclerosis." (PMID 34395445, 2021). "A study of nicotine exacerbating atherosclerosis showed that increased intracellular ROS caused macrophages pyroptosis, which is manifested by the assembly of NLRP3 inflammasome, the cleavage of caspase-1 and the increase of IL-1β, IL-18, and GSDMD production." (PMID 34122076, 2021). "Thus, in addition to lipid-lowering therapy, ameliorating vascular inflammation may also be a crucial strategy for treating atherosclerosis, and suppression of GSDMD activation may be a promising therapeutic strategy." (PMID 37593179, 2023).
atherosclerosis (continued). "The idea of combining lipid-lowering therapeutics with anti-inflammatory drugs is getting increasingly recognized, and targeting GsdmD in combination of LDL lowering therapies such as statins or PCSK9 antibody may serve as potential therapeutic to treat atherosclerosis and CVD." (PMID 34395445, 2021). "Another mechanism by which GsdmD can promote atherosclerosis could be via regulating pyroptosis." (PMID 34395445, 2021). "Therefore, targeting the caspase 11-gasdermin D pathway may serve as an alternative strategy for the treatment of atherosclerosis." (PMID 33981234, 2021). "For example, in a mouse model of atherosclerosis induced by a HFD, the protein levels of NLRP3, ASC, GSDMD-N, IL-1β, and IL-18 were significantly elevated; GSDMD-mediated pyroptosis then accelerated the progression of atherosclerosis." (PMID 41194915, 2025). "We identified a set of genes (GSDMD, CASP1, NLRC4, AIM2, and IL18) closely related to atherosclerosis, particularly in atherosclerotic lesions with high pyroptosis scores." (PMID 38167983, 2024). "We used IHC to preliminarily detect the expression of GSDMD, CASP1, NLRC4, AIM2 and IL18 in advanced atherosclerosis plaques of patients." (PMID 38167983, 2024). "Thus, the inhibition of caspase-1, NLRP3, or GSDMD in dyslipidemic and inflammatory contexts prevents endothelial pyroptosis and improves endothelial survival, thereby preserving vascular intima integrity, reducing vascular inflammation, and further attenuating the progression of atherosclerosis." (PMID 37894840, 2023). "The aim of the present study was to investigate the therapeutic effects of inhibition of GSDMD activation by Z-LLSD-FMK, Z-YVAD-FMK, and the combination of both on vascular inflammation and atherosclerosis." (PMID 37593179, 2023). "Thus, GsdmD KO may dampen the progression of atherosclerosis due to reduced formation of NETs." (PMID 34395445, 2021). "The inhibition of GSDMD can reduce pyroptosis induced by several inflammasome components, such as NLPR3 and inflammatory caspases, and that pharmacological inhibition of GSDMD exerts protective effects on atherosclerosis." (PMID 40045452, 2025). "In detail, GSDMD activation leads to mitochondrial rupture and mtDNA leakage, which in turn activates the stimulator of interferon genes (STING)- interferon regulatory factor 3 (IRF3)/NF-κB axis to mediate atherosclerosis progression." (PMID 40356915, 2025). "Similarly, our investigation of diabetic atherosclerosis of ApoE−/− mice revealed the enhanced expression level of NLRP3-ASC and GSDMD in the atherosclerotic plaques of endothelial cells with aortic sinus." (PMID 36425580, 2022). "Although a large amount of basic data reveal the role of GSDMD in atherosclerosis progression, there is still no clinical evidence to elucidate the association between GSDMD and AMI." (PMID 36544106, 2022). "Nlrp3 inflammasome is activated in advanced human atherosclerotic plaques, but the role of GsdmD in sterile inflammatory diseases such as atherosclerosis is not yet described." (PMID 34395445, 2021). "In contrast to Nlrp3 inflammasome and IL-1β, the direct role of GsdmD in atherosclerosis is not yet clear." (PMID 34395445, 2021). "Though Nlrp3/AIM2 and IL-1β nexus is an emerging atherogenic pathway, the direct role of GsdmD in atherosclerosis is not yet fully clear." (PMID 34395445, 2021). "Our data show that GsdmD mediates inflammation-induced defects in RCT and promotes atherosclerosis." (PMID 34395445, 2021). "Our data show a novel role of GsdmD in the progression of atherosclerosis, independent of lipid levels." (PMID 34395445, 2021).
atherosclerosis (continued). "Finally, the authors concluded that AIM2 promotes the activity the N-terminal domain of GSDMD (GSDMD-N), which is required for pyroptosis, thereby accelerating pyroptosis in VSMC and unmasking AIM2 as an active participant in atherosclerosis." (PMID 33263007, 2020). "Suppression of GSDMD activation by Z-LLSD-FMK or Z-YVAD-FMK remarkably reduced lesion development in ApoE−/− mice, suggesting that inhibition of GSDMD activation may be a promising strategy for the treatment of atherosclerosis." (PMID 37593179, 2023). "Our findings suggest that blocking GSDMD activation by the novel human GSDMD polypeptide inhibitor Ac-FLTD-CMK may be a novel and effective strategy for reducing atherosclerotic lesion development for the treatment of atherosclerosis." (PMID 37593179, 2023). "In addition, with the application of GSDMD−/− mice, studies clarified that the reduction of GSDMD can effectively inhibit the level of inflammation and pyroptosis in mice, thereby improving the formation of arterial plaques and delaying atherosclerosis." (PMID 36544106, 2022). "The role of GsdmD in sterile inflammatory diseases, such as atherosclerosis, is not yet clear." (PMID 34395445, 2021). "Thus, GsdmD may play role in Nlrp3 inflammasome mediated dampening of RCT and in promoting the progression of atherosclerosis, either by virtue of increasing IL-1β release from live inflamed immune cells or by promoting pyroptotic cell death in advanced atherosclerotic plaques." (PMID 34395445, 2021). "The presence of cleaved N-terminal fragment of GsdmD in aortic tissue from atherosclerotic plaque-bearing mice may indicate the role of pyroptotic cell death in the progression of atherosclerosis, but is not a conclusive evidence as GsdmD can also get cleaved in living macrophages." (PMID 34395445, 2021).
non-small cell lung carcinoma (43 papers, 2019 to 2025). A group of at least three distinct histological types of lung cancer, including non-small cell squamous cell carcinoma, adenocarcinoma, and large cell carcinoma. "In non-small cell lung cancer, GSDMD expression is upregulated, supports metastasis, and is associated with a poor prognosis and in general, GSDMD is differentially expressed in cancer." (PMID 37771587, 2023). "It is shown the higher expression of GSDMD, which is the classical executioner of pyroptosis, is associated with larger tumor sizes and more advanced tumor-node-metastasis stage in non-small cell lung cancer (NSCLC) patients." (PMID 35819638, 2022). "In non-small cell lung cancer, GSDMD can be cleaved by caspases, which causes cancer cells to scorch." (PMID 35034587, 2022). "The protein level of GSDMD was positively associated with the aggressiveness of non-small cell lung cancer (NSCLC)." (PMID 34298833, 2021). "Furthermore, GSDMD was found to be up-regulated in non-small cell lung cancer, and its elevated expression was associated with tumor metastasis and poor prognosis." (PMID 37950289, 2023). "GSDMD protein levels were associated with a significant increase in non-small cell lung cancer." (PMID 36120543, 2022). "Conversely, GSDMD protein levels were remarkably increased in non-small cell lung cancer (NSCLC) compared to adjacent controls and were associated with greater tumor size, more advanced tumor node metastasis stages, and, in lung adenocarcinoma (LUAD), poorer prognosis." (PMID 34429144, 2021). "In contrast, non-small cell lung cancer (NSCLC) exhibits an upregulation of GSDMD expression, which correlates with a poor prognosis." (PMID 41291696, 2025). "GSDMD was also found to be over-expressed in non-small cell lung cancer (NSCLC), and its ablation enhanced the rate of cancer cell apoptosis." (PMID 38898209, 2024). "For instance, GSDMD is upregulated in hepatocellular carcinoma and non-small cell lung cancer, with higher levels of GSDMD expression in tumor tissues predicting a less favorable patient survival outcome." (PMID 38066523, 2023). "This NLRP3/caspase-1/GSDMD pyroptosis pathway in response to simvastatin in colon cancer cells was consistent with the previsous study in non-small cell lung cancer." (PMID 37974278, 2023). "The expression of GSDMD increased in non-small cell lung cancer and metastatic melanoma, which increased the invasion and apoptosis of tumors." (PMID 37483501, 2023). "A previous study confirmed that GSDMD is highly expressed in non-small cell lung cancer (NSCLC), and the expression level of GSDMD was associated with tumor size and stage." (PMID 37371484, 2023). "NLRP3 inflammasome-mediated pyroptosis promotes the progression of lung adenocarcinoma but inhibits the progression of non-small-cell lung cancer, while GSDMD-mediated pyroptosis promotes the progression of non-small-cell lung cancer." (PMID 35246158, 2022). "The anti-tumour action of Cucurbitacin B was found to involve the activation of GSDMD-dependent pyroptosis of non-small cell lung cancer (NSCLC) cells in vitro and in vivo." (PMID 35517821, 2022). "A previous study had confirmed that the expression of GSDMD in non-small cell lung cancer (NSCLC) tissue is significantly higher, and is related to larger tumor size, more advanced stages, and other more aggressive characteristics." (PMID 35311148, 2022). "Polyphyllin VI induced caspase-1-mediated pyroptosis via the induction of the ROS/NF-κB/NLRP3/GSDMD signal axis in non-small-cell lung cancer." (PMID 34764819, 2021). "As a first example of a possible detrimental role of GSDMD, its expression was found to be upregulated in malignant cells compared to adjacent tissues in non-small-cell lung carcinoma (NSCLC)." (PMID 34490126, 2021). "Previous study revealed that low expression level of gasdermin D (GSDMD) correlated with a favorable prognosis in non-small-cell lung cancer." (PMID 35198000, 2021).